MYCN (MYCN proto-oncogene, bHLH transcription factor)
Diseases named in the same sentence as MYCN in open-access papers (continued):
Sharing a sentence is not in itself a finding about the gene and the disease.
tumor (continued). "MYCN copy number alteration (amplification) was seen in one tumor while CDK6 amplification was not seen." (PMID 29869738, 2018). "MYCN usually has a very short half-life, but after amplification it is highly expressed and forms heterodimers with MAX to act as a transcriptional factor and support constant NB tumor growth." (PMID 29371588, 2018). "This miRNA has anti-proliferative effects and has been found to target MYCN.miR-34a is located on chromosome 1 and it is not surprising that lower levels are expressed in tumours with/or due to a 1p deletion." (PMID 28103887, 2017). "However, the weak p27 immunoreactivity suggests that it is expressed in low levels in all MYCN‐amplified tumors, except the RB1−/− tumor, UPEN‐RB‐201, where it is highly expressed in both well and poorly differentiated areas of the tumor." (PMID 28211617, 2017). "Histopathological examination of paraffin-embedded tumor xenograft sections revealed lower levels of a proliferation marker (Ki67), an angiogenesis marker (CD31), and MYCN expression in didymin-treated NB xenografts as compared to untreated, which further supports the in vitro results." (PMID 28187004, 2017). "All tumors maintained diffuse strong nuclear MYCN expression, and cytoplasmic labeling for markers used to characterize human NBL (TH, TRKB, and Chromogranin A) was generally focal to multifocal in small to moderate numbers of tumor cells." (PMID 29238067, 2017). "This experimental design was planned to reflect the status of a heterogeneous tumor containing cell clones with and without a MYCN amplification." (PMID 29156716, 2017). "The primary objective was quantification of tumour native T1 and R2*, imaging biomarkers previously shown to be sensitive to successful treatment response and haemodynamic vasculature within the Th-MYCN and Th-ALKF1174L/Th-MYCN mice, measured at 7T." (PMID 28787429, 2017). "Whereas three high-risk patients with relapsed tumors with neither MYCN amplification nor ARID1B mutations were rescued with salvage treatment after relapse, two relapsed patients with ARID1B mutations died of tumor progression." (PMID 28521285, 2017). "According with Versteeg data set, there is not difference in NEO1 expression in tumor samples with or without MYCN amplification." (PMID 28038459, 2017). "The samples are usually tissue from primary tumors; however, for those patients who need chemotherapy prior to surgery, timely identification of the level of MYCN gene is not possible because of the limited nature of tumor biopsies." (PMID 28367105, 2017). "Overall, our data suggest that NBL tumor cells lacking MYCN amplification recruit and polarize macrophages to an M2-like phenotype, which in turn enhance NBL proliferation and growth through up-regulation of the MYC protein." (PMID 29207662, 2017). "High-level focal amplification of MYCN and RB1 mutations by was not considered significantly inversely correlated because tumor T21 acquired both alterations (single nucleotide frameshift deletion in exon 15 of RB1; NM_000321:c.1397delA:p.E466fs)." (PMID 27126562, 2016). "PlGF inhibition by virally-expressed shPlGF reduced tumor growth in a MYCN-non-amplified NB xenograft model by affecting proliferation of tumor cells without remodeling of the vascular network." (PMID 27669225, 2016). "They first observed on sections MYCN amplified ECs, in proportions that correlated with tumor grade, and ruled out pericytes as being tumor-derived." (PMID 27738435, 2016).
tumor (continued). "Immunoblotting of tumor tissue confirmed that NVP-BEZ235 blocked PI3K (AKTSER473/308, GSK3βSER9) and mTOR signaling (RPS6SER240/244, 4EBP1THR37/46) coincident with down-regulation of intra-tumoral MYCN protein." (PMID 27438153, 2016). "Intriguingly, we demonstrated that PlGF inhibition reduced the proliferation of tumor cells in established MYCN-non-amplified NB xenografts resulting in suppression of tumor growth, but unexpectedly did not alter the tumor vasculature." (PMID 27669225, 2016). "In particular, approximately 50% of the microvessels in experimental tumors and 20–80% in primary NB masses were of tumor origin, as demonstrated by EC expression of classical endothelial markers (CD31, CD105, and von Willebrand factor) and amplification of the MYCN oncogene." (PMID 26925422, 2016). "Thus, mRNA profiling allowed both, the recognition of tumor-specific and MYCN-specific signatures in LSL-MYCN;hGFAP-Cre induced tumors." (PMID 27769070, 2016). "By contrast, the EGFP+ sympathoadrenal cells in the IRG of nf1a-/- homozygous zebrafish expanded much more rapidly, with an average 6.61-fold expansion rate within the 3 week period (nf1a-/-;nf1b+/+; MYCN;EGFP) and tumor development in 9 of 10 fish before 6 weeks of age." (PMID 27130733, 2016). "We find, however, that MYCN overexpression alone in primary SAPs is not sufficient for tumor formation in nude mice." (PMID 26222553, 2015). "Subsequent immunochemistry staining confirmed that expression of GLS2, but not GLS1, was markedly elevated in MYCN-amplified tumors (samples 27, 9638 and 35313) when compared with the low-stage, non-amplified tumor (sample 20641)." (PMID 26528759, 2015). "Formalin-fixed paraffin-embedded tumor tissues were collected from 338 M0 patients (>4.0 years at diagnosis) for pathology review and assessment of the WNT subgroup (MBWNT) and genomic copy-number defects (chromosome 17, MYC/MYCN, 9q22 (PTCH1) and DNA ploidy)." (PMID 26420814, 2015). "As a next step, we performed experiments aiming at demonstrating more directly that the tumor promoting effect of ATM silencing is not mediated by MYCN." (PMID 26053094, 2015). "Using qRT-PCR analysis in a cohort of 49 NB tumours, this study found 7 T-UCRs to be overexpressed in MYCN amplified tumours relative to the non-amplified ones." (PMID 26087192, 2015). "Assuming that miRNAs would have more impact on MYCN expression levels and activities in MYCN non-amplified cells, we chose to assess miRNA correlations with MYCN mRNA levels and activity only in this tumor subset to infer a potential regulatory relationship." (PMID 25294817, 2015). "Our studies here show that integrin α4 is expressed more frequently in primary tumor samples from patients lacking MYCN amplification." (PMID 25973900, 2015). "On the basis of their MYCN gene copy number status, these tumor samples can be divided into MYCN-amplified (n=93) or non-MYCN-amplified (n=550) tumors." (PMID 25277194, 2014). "The present study demonstrated a significant difference in both the size and number of neurotubules within MYCN amplified tumours compared to the non-MYCN amplified tumours, which has not been reported previously." (PMID 24679140, 2014). "Ultrastructural features of neuroblastic tumours are well-described but there are no data regarding ultrastructural findings specifically in relation to MYCN status." (PMID 24679140, 2014). "With this in mind, we characterized 18 parental NB cell lines (cell lines directly derived from the original tumor and not by in vitro cell subcloning) in terms of MYCN levels." (PMID 24515800, 2014). "Among 1100 aCGH profiles, we found a total of 12 tumours showing amplification of one or several loci distinct from MYCN without any evidence of MNA (1%)." (PMID 25013904, 2014).
tumor (continued). "Type 1 tumours are characterised by a hyperdiploid to near-triploid chromosome number with no/few structural aberrations, and absence of MYCN amplification." (PMID 23555645, 2013). "MYCN, as well as c-MYC, was widely studied as a transcriptional activator leading to the conclusion that up-regulated target genes are responsible for many aspects of the tumor malignancy." (PMID 23482921, 2013). "Interphase FISH showed MYCN gain nuc ish(MYCN×3-10) in the tumor cells, while evaluation of metaphase chromosomes showed no signal translocation neither to dmin nor to other chromosomes." (PMID 24131700, 2013). "Although in our studies we investigated MYCN amplification but not MYCN protein expression, it is well-known that MYCN-amplified tumor usually over-express the corresponding protein." (PMID 23162796, 2012). "For example, RASSF5 methylation highly correlated to MYCN amplification and INRG stage M. Furthermore, high methylation of RASSF6 was correlated to unfavorable outcome, 1p deletion and MYCN amplification in our tumor material." (PMID 22695170, 2012). "Samples assigned to hierarchical clusters h2 and h4 consisted of high stage tumours (stage 3-4) with high frequency of del11q without MYCN amplification, thus corresponding to the genomic subtype 2A." (PMID 21492432, 2011). "Recent data from miRNA profiling studies show that let-7e, mir-29a and mir-29c are significantly lower expressed in MNA primary tumours compared with non-MNA tumours, supporting the idea that they act as endogenous MYCN regulators." (PMID 21654684, 2011). "High expression of Mash1 was significantly associated with advanced tumor stage (p = 0.004) but not with age (p = 0.81), TrkA expression (p = 0.4), MYCN copy number (p = 0.11), tumor origin (p = 0.2) and Shimada classification (p = 0.45)." (PMID 21573214, 2011). "However, samples assigned to the p4 cluster showed a significantly lower expression of MYCN and ALK compared to the MNA-specific cluster p3, which indicate an alternative progression pathway within tumours assigned to the fourth cluster." (PMID 21492432, 2011). "Their MYCN mRNA and protein levels exceed the levels of high-risk non-MNA tumours with poor outcome, but do not reach those of MNA tumours." (PMID 21654684, 2011). "Using the human B-cell derived p493-6 and the human NB-derived Tet21 N cell lines with conditional expression of c-MYC and MYCN respectively, we show that a limited number of agents, acting through distinct mechanisms, are more effective in MYC overexpressing tumor cells." (PMID 22132187, 2011). "This theory should explain the apparent paradox of a ubiquitous factor B-MYB-being upstream of a tissue specific factor –MYCN- and clarify why MYCN is not activated in the vast cohort of non-neuronal tumours where B-MYB is overexpressed or amplified." (PMID 21304178, 2010). "For MYCN, it has been demonstrated that the relative expression-levels are significantly higher in NBs with MYCN-amplification as compared to non-amplified tumours." (PMID 19615087, 2009). "In contrast to GATA-4, tumours without MYCN-amplification exhibited higher expression values than those with MYCN-amplification (P<0.001)." (PMID 19707195, 2009). "This 15 miRNA expression signature requires validation in an independent tumor set, and represents a method of patient stratification that is independent of MYCN amplification status." (PMID 19924232, 2009). "Since the majority (9 out of 15) of unfavourable tumours show MNA, one could speculate that many of the differentially expressed transcripts could be part of the MYCN downstream signalling pathway and the lower expression would be merely an effect of MNA." (PMID 19686582, 2009).
tumor (continued). "MYCN-amplified tumours (n=32 out of 33; one specimen was not available for GATA-4 analysis) expressed significantly more GATA-4 than MYCN-nonamplified (n=218) tumours (P=0.001)." (PMID 19707195, 2009). "In particular, stage 4s tumours showed higher expression levels of a significant set of genes localized on chromosome 1p when compared both to infant MYCN-amplified as well as nonamplified stage 4 NB tumours." (PMID 19192278, 2009). "The expression of FOG-2 was higher in tumours without MYCN-amplification and in tumours with favourable PAM prediction." (PMID 19707195, 2009). "GATA-2 showed significantly higher expression values in MYCN-nonamplified compared with MYCN-amplified tumours (P<0.001)." (PMID 19707195, 2009). "Despite the small set of tumours, differential gene expression between stage 4s and stage 4 < 18 months MYCN not amplified tumours (9 cases) was also investigated." (PMID 19192278, 2009). "The prognostic value of MYCN amplification is so strong that, in a clinical setting, the need for reliable genomic typing mainly concerns MYCN non-amplified tumours." (PMID 17579628, 2007). "Applying a minimum follow-up time of five years after initial diagnosis, gene expression profiles of MYCN non-amplified tumours with advanced INSS stage (3 or 4) from 66 patients were obtained in total from both studies." (PMID 17531100, 2007). "Genomic profiles provide a comprehensive overview of genomic changes in NB and are of prognostic impact in patients without MYCN amplification, making them a help in the management specifically of low stage tumours." (PMID 17579628, 2007). "Using the set of 72 significant genes for a hierarchical clustering of MYCN amplified stage 3 or 4 tumours and MYCN non-amplified tumours with stages 1, 2, 4s, both prognosis groups are clearly separated." (PMID 17531100, 2007). "The presented results characterise a patient outcome specific set of differentially expressed genes in MYCN non-amplified advanced stage tumours." (PMID 17531100, 2007). "In this study, we combined gene expression data from two different studies to investigate the differences in gene expression for advanced stage MYCN non-amplified tumours with contrasting outcome at five years after initial diagnosis." (PMID 17531100, 2007). "Case 30 had the resectable tumour with MYCN 3 copies by the Southern blot analysis and was not classified into the high-risk group." (PMID 16670717, 2006). "However, when the Ki67 labelling index mean value of the seven MYCN amplified NTs was calculated (48.9±5.5), it was found to be significantly higher than in the 23 high MKI (20.3±12.0) and the 30 low MKI tumours (P<0.001)." (PMID 16755292, 2006). "MYCN gene has been analysed by the Southern blotting method for whole tumours, but this method is not able to evaluate the status MNA in individual NB cells." (PMID 16670717, 2006). "Clinical results achieved prior to 1991 by us and by others clearly showed that patients with MYCN-amplified tumours have a worse prognosis than those without." (PMID 11953858, 2002). "Targeting this pathway with the AURKA inhibitor PHA739358 in combination with Olaparib markedly suppressed tumour growth in both cell line derived and patient-derived xenograft models, underscoring a mechanistic and therapeutic convergence between AURKA and PARPi in MYCN-driven malignancies." (PMID 41561634, 2025). "Therefore, MYC and MYCN are probably not the primary ‘drivers’, but instead are acquired after malignant transformation and probably accelerate tumour growth." (PMID 40335697, 2025). "The tumours classified as MYCN-type showed genomic amplification of MYCN (MNA); however, some MYCN-type cases lacked evident MNA, suggesting that epigenetic states might be influenced by other factors such as activating ALK mutations." (PMID 40713849, 2025).
tumor (continued). "Additionally, MYCN has been demonstrated to interact with additional oncogenic factors, including hypoxia-inducible factor 1-alpha (HIF-1α), thereby enhancing its influence on tumor progression." (PMID 40429864, 2025). "Hemizygous Th-MYCN+/− mice had a survival probability of 30% when the PA2G4 gene was wildtype, whereas both hemizygous PA2G4WT/DelEx1–5 and homozygous PA2G4DelEx1-/DelEx1–5 knockout equally increased tumor-free survival probability of the homozygous Th-MYCN+/+ mice to 80%." (PMID 41002386, 2025). "Furthermore, ONC201 failed to decrease the number of tumor vessels in non-MYCN-amplified SK-N-AS and SK-N-FI xenografts, whereas it induced a significant decrease in neovascularization within MYCN-amplified SK-N-DZ xenografts." (PMID 40210723, 2025). "Notably, in all cases, reconstruction of the putative phylogenetic trees showed that MYCN amplification was not the initiating event for the tumour." (PMID 40335697, 2025). "Especially in the case of MYCN-amplified relapsed WT, the combination of bortezomib with an HDAC inhibitor could improve overall survival rates through a synergistic effect that has already been described in other tumor entities." (PMID 39740515, 2025). "Additionally, other findings suggest that besides being associated with cellular senescence, the AURKA gene can drive tumor progression through the LIN28B-RAN-AURKA signaling pathway, and it also plays a role in maintaining N-MYC stability in MYCN-amplified NB." (PMID 39135779, 2024). "MYCN is especially enriched in this tumour, although no gene amplifications have been described." (PMID 39126064, 2024). "To evaluate whether FAK activity influences GSK3β, we treated ALK/MYCN tumor cells with or without the FAK inhibitor defactinib." (PMID 38451815, 2024). "The presence of tumor cells with MYCN copy number gain while still not having acquired extra copies of 17q was ascertained in 5/6 cases, the exception being S3 in which neither scWGS nor FISH could identify such cells." (PMID 39419962, 2024). "Furthermore, we immortalized cells of a RB1 mutated, MYCN amplified and trefoil factor family peptid 1 (TFF1) positive RB tumor and RB derived non-tumor stromal tissue." (PMID 39695086, 2024). "Furthermore, the patients with these heterogeneous tumours were found to have a significantly better survival rate, especially when the MYCN gene was not amplified." (PMID 39715281, 2024). "Applying these gene signatures to the NB tumour data, we found that expression signatures C5* (sensory neuron-like cells) and C13* (differentiating SYM-like cells), jointly separated MYCN-amplified and non-amplified tumours, as well as tumours at different clinical stages." (PMID 38702304, 2024). "Moreover, in the context of combined MYCN and PRMD6 overexpression, we did not observe a modulation of tumor onset or progression in comparison to MYCN overexpressing NES cells." (PMID 38992221, 2024). "Additionally, there was a second MYCN-non-amplified high-risk clone with a higher stroma signature and an immunosuppressive TME, characterized by Treg, tumor-associated macrophages (TAMs), and MDSC populations." (PMID 38791942, 2024). "However, translation in MYCN‐nonamplified tumor cells (RB654 and SK‐N‐SH) was not significantly affected by ceftriaxone treatment, even at the high dose (9 mm ceftriaxone) in RB654." (PMID 37975412, 2024). "WNT-C59 specifically reduced EdU incorporation in ALK/MYCN tumor cells but not in MYCN tumor cells." (PMID 38451815, 2024). "Consistent with the viability‐based IC50 values, the dose of ceftriaxone used to inhibit 50% colony formation of MYCN‐amplified tumor cells was lower than that used in MYCN‐nonamplified tumor cells, confirming growth inhibition of MYCN‐driven tumors upon ceftriaxone treatment." (PMID 37975412, 2024).